ZAR1 (zygote arrest 1)
Diseases named in the same sentence as ZAR1 in open-access papers (continued):
Sharing a sentence is not in itself a finding about the gene and the disease.
cancer (continued). "With the present work, we report ZAR1 as a cancer biomarker and also elucidate its role in human cancer using state-of-the-art methylation sequencing, transcriptomic approaches, mass spectrometry for the identification of interacting partners, and epigenetic reactivation by CRISPR-dCas9." (PMID 31801617, 2019). "ZAR1 hypermethylation significantly correlates with its expression reduction in cancers." (PMID 31801617, 2019). "Epigenetic therapy can reactivate the ZAR1 tumour suppressor in cancer." (PMID 31801617, 2019). "Here, we add evidence for ZAR1 hypermethylation in further cancer types." (PMID 31801617, 2019). "Mutation of ZAR1 is a non-frequent event in cancer patients across cancer types with an incidence of <2% (n = 4440 TCGA tumours, 15 cancer types, analysed using)." (PMID 31801617, 2019). "With this tool on-hand, we could not only study ZAR1 expression in primary cancer samples and correlate expression with ZAR1 promoter methylation but also study interacting partners, which would give insight into its network and signalling pathways." (PMID 28588743, 2017). "ZAR1 inhibited cancer cell growth by arresting cell cycle progression." (PMID 28588743, 2017). "We demonstrated that ZAR1 could repress growth of cancer cell lines by inhibiting cell cycle progression." (PMID 28588743, 2017). "Furthermore, ZAR1 was characterised by the ability to block tumour growth through the inhibition of cell cycle progression in cancer cell lines." (PMID 28588743, 2017). "Additionally, we characterised the tumour suppressive properties of ZAR1 in cancer cells." (PMID 28588743, 2017). "Cancer cell lines (A427, A549, H322, HTB171 and HeLa) with ZAR1 promoter hypermethylation and missing ZAR1 expression were chosen for testing reexpression of ZAR1 under demethylation treatment." (PMID 28588743, 2017). "The binding of ZAR1 to WEE2 could not be detected due to lack of expression in cancer cells." (PMID 31801617, 2019).
infection (5 papers, 2010 to 2025). The state of being infected such as from the introduction of a foreign agent such as serum, vaccine, antigenic substance or organism. "The rks1/sut1 double mutants showed a similar level of susceptibility as the Oy-0 control, indicating that RKS1/ZAR1 and SUT1 together represent the main resistance genes in Col-0 that halt Xcc in the initial phase of the infection." (PMID 40587573, 2025). "This pseudokinase serves as a decoy to HopZ1a, an infection effector, in the ZAR1-mediated immunity response." (PMID 32293271, 2020). "Heavy trypan blue staining indicative of an HR was observed in zar1-1 leaves infiltrated with PtoDC3000(avrRpt2) and Col-0 leaves infiltrated with PtoDC3000(hopZ1a) or PtoDC3000(avrRpt2) at 12 hours post-infection." (PMID 20368970, 2010). "However, RKS1/ZAR1 resistance is also effective in tissue types that represent late infection stages, i.e., xylem and mesophyll." (PMID 40587573, 2025). "It remains to be shown whether the interaction of the ZRK13 protein from Bla-6 with the ZAR1 resistosome upon infection with On is responsible for the resistance." (PMID 37025130, 2023). "Next, we evaluate the resistance level that RKS1/ZAR1 and SUT1 provide at different stages of the infection using the wildtype strain Xcc8004 Tn7:lux strain." (PMID 40587573, 2025). "Earlier, we showed that the Arabidopsis accession Col-0 shows a high level of resistance to the vascular bacterial pathogen Xcc8004 in guttation-based infections and that this response was independent of XopAC recognition by RKS1/ZAR1." (PMID 40587573, 2025).
tumor (5 papers, 2017 to 2023). "Epigenetic therapy using the CRISPR-dCas9 method accurately targets and reactivates zygote arrest 1 (ZAR1), allowing it to regain its role as a tumor suppressor." (PMID 34899345, 2021). "Next, we aimed to understand if the ZAR1 zinc-finger is involved in its tumour suppression and investigated the ZAR1 coding region." (PMID 31801617, 2019). "With the present study, we demonstrated tumour suppressor properties of ZAR1, which were dependent on its zinc-finger domain." (PMID 31801617, 2019). "We further established that the carboxy (C)-terminally present zinc-finger of ZAR1 is relevant for its tumour suppression function and its protein partner binding associated with the mRNA/ribosomal network." (PMID 31801617, 2019). "Using the CRISPR-dCas9 tools, we were able to prove that epigenetic editing and reactivation of the ZAR1 tumour suppressor is feasible." (PMID 31801617, 2019). "ZAR1 promoter methylation increased from matching control tissues to tumour samples (LT1 to LN1, LT3 to LN3, LT39 to LN39)." (PMID 28588743, 2017). "ZAR1 intragenic methylation (first exon to intron 1) in sporadic bladder cancer was decreased in high-grade vs. low-grade tumours." (PMID 28588743, 2017). "Our focus is the exciting and novel role of ZAR1 as a tumour suppressor in humans." (PMID 31801617, 2019). "This suggests that several CpGs might be analysed for ZAR1 methylation in function of the tumour of interest." (PMID 31801617, 2019). "ZAR1 can inhibit cell cycle progression and may serve as a tumor suppressor." (PMID 36964402, 2023). "In matching tumours and control tissues, we observed that NSCLC primary tumour samples exhibited a tumour-specific promoter methylation of ZAR1 in comparison to the normal control lung tissue." (PMID 28588743, 2017). "In primary tumour samples from SCLC, the ZAR1 promoter was methylated in 5 out of 23 (22%) and in NSCLC, 16 out of 21 (76%)." (PMID 28588743, 2017).
ZAR1 also shares sentences with these, for which no sentence is quoted: brain cancer (1 paper); brain tumors (1); cervix cancer (1); colon carcinoma (1); Cornelia de Lange syndrome-4 (1); non-small cell lung carcinoma (1); Ovarian Insufficiency (1); renal clear cell carcinoma (1).